BRK1 (BRICK1 subunit of SCAR/WAVE actin nucleating complex)
Description:
Involved in regulation of actin and microtubule organization. Part of a WAVE complex that activates the Arp2/3 complex. As component of the WAVE1 complex, required for BDNF-NTRK2 endocytic trafficking and signaling from early endosomes (By similarity).
Synonyms: C3orf10; HSPC300; MDS027; hHBrk1
Tractability: Small molecule: a structure with a bound ligand is known. PROTAC: ubiquitination databases record sites on it; its protein half-life has been measured.
Gene: Protein-coding gene on chromosome 3 (10,115,673 to 10,127,190, forward strand). Ensembl gene ENSG00000254999.
Subcellular location: Cytoplasm, cytoskeleton
Subcellular location (Human Protein Atlas): Nuclear speckles; Cell Junctions
Pathways (Reactome):
Signal Transduction: RAC1 GTPase cycle; RAC2 GTPase cycle; RAC3 GTPase cycle; RHO GTPases Activate WASPs and WAVEs; VEGFA-VEGFR2 Pathway
Disease: FCGR3A-mediated phagocytosis
Immune System: Regulation of actin dynamics for phagocytic cup formation
Gene Ontology:
Molecular function: identical protein binding; protein binding; protein-containing complex binding; small GTPase binding
Biological process: positive regulation of Arp2/3 complex-mediated actin nucleation; positive regulation of lamellipodium assembly; positive regulation of protein-containing complex assembly; Rac protein signal transduction; cell motility; regulation of actin polymerization or depolymerization; actin filament organization
Cellular component: extracellular exosome; SCAR complex; cytosol; lamellipodium; cytoskeleton
Genetic constraint (gnomAD): Loss-of-function variants: 5 observed, 5.31 expected, observed/expected ratio (o/e) 0.94, 90% interval 0.49 to 1.77. That is too few expected variants to judge how well the gene tolerates losing a copy. Missense variants: 44 observed, 68.32 expected, observed/expected ratio (o/e) 0.64, 90% interval 0.5 to 0.83. Synonymous variants: 29 observed, 24.49 expected, observed/expected ratio (o/e) 1.18, 90% interval 0.88 to 1.61.
Homologues: Orthologues: chimpanzee BRK1 (100% identical), macaque BRK1 (100% identical), guinea pig BRK1 (99% identical), mouse Brk1 (99% identical), rabbit BRK1 (99% identical), rat Brk1 (99% identical), pig BRK1 (97% identical), tropical clawed frog brk1 (97% identical), Drosophila melanogaster HSPC300 (72% identical).
Diseases named in the same sentence as BRK1 in open-access papers:
BRK1 is named in the same sentence as 13 diseases in open-access papers, as found by Europe PMC text mining. Sharing a sentence is not in itself a finding about the gene and the disease. The quoted sentences say what the papers report.
renal cell carcinoma (3 papers, 2005 to 2025). "These included two isoforms of a fusion involving the genes BRK1 and VHL, whose co-deletion has previously been associated with the prevalence and severity of renal-cell carcinoma." (PMID 22761941, 2012). "Of these, BRK1:VHL represents the fusion of two genes that have previously been shown to co-operate in the development of renal cell carcinoma." (PMID 22761941, 2012). "Presence of mutations in the BRK1 gene in patients one and two could explain why they have not developed renal cell carcinoma as these mutations have been associated with a reduced risk of renal cell carcinoma." (PMID 41302074, 2025).
breast carcinoma (2 papers, 2023 to 2024). "For instance, large deletions of VHL and C3orf10, as well as BRK1, have been associated with lower lifetime risk of kidney cancer, whereas the deletion encompassing VHL and the FANCD2 gene may be linked to an increased susceptibility to breast cancer." (PMID 39336783, 2024). "The high expression of disulfidptosis genes (e.g., SLC3A2, RPN1, BRK1, ACTR2, ACTR3, SLC7A11, and NCKAP1) in the KM analysis of breast cancer indicated the poor prognosis of patients." (PMID 38035071, 2023).
pheochromocytoma (2 papers, 2012 to 2021). "C3orf10:VHL or BRK1:VHL (#8) - VHL is a tumour suppressor gene deleted in von Hippel Lindau disease, an autosomal dominant familial cancer syndrome that can give rise to pheochromocytoma and tumours of the kidney, central nervous system, pancreas, retina and epididymis." (PMID 22761941, 2012).
asthma (1 paper, 2018). "There were common genes between these two study groups, where five genes were up-regulated (ATP5E, BRK1, KCNJ6, RNASEH2C, and RPL9) and one gene (RAB5B) was down-regulated in patients with mild and severe asthma compared with normal individuals." (PMID 30038057, 2018).
cervical squamous cell carcinoma (1 paper, 2025). A squamous cell carcinoma arising from the cervical epithelium. "Notably, NDUFA11 and BRK1 showed significant associations with patient survival, highlighting their prognostic importance in cervical squamous cell carcinoma." (PMID 40305445, 2025). "Among the four identified hub genes, NDUFA11 and BRK1 exhibited significant variations in patient survival, impacting the prognostic outcomes of patients with cervical squamous cell carcinoma (CESC)." (PMID 40305445, 2025).
tumor (3 papers, 2012 to 2025). "This could be explained by the presence of a mutation in the BRK1 gene which has been previously shown to confer protection to VHL patients from developing this type of tumor." (PMID 41302074, 2025).
infection (2 papers, 2020 to 2023). The state of being infected such as from the introduction of a foreign agent such as serum, vaccine, antigenic substance or organism. "E-30 infection leads to a down-regulation of proteins such as RADIXIN, PFDN6, DYNLB1, and BRK1." (PMID 33321840, 2020).
BRK1 also shares sentences with these, for which no sentence is quoted: kidney cancer (2 papers); Nephropathy (1); retinal angiomas (1); tumours of the kidney (1); type A thymomas (1); von Hippel-Lindau disease (1).